CD4 (CD4 molecule)
Diseases named in the same sentence as CD4 in open-access papers (continued):
Sharing a sentence is not in itself a finding about the gene and the disease.
glioma (continued). "FPRL1 mRNA was, however, not detected in HepG2 (hepatoblastoma), Huh7 (hepatoma), or NP-2/CD4 (CD4-transduced glioma) cells." (PMID 18577234, 2008). "Expression of FPRL1 mRNA was also detected in human cells derived from a wide variety of origins, such as PBLs, C8166 (T cells), Molt4#8 (T cells), 293T (embryonic kidney cells), HOS (osteosarcoma cells), U251MG (astrocytoma cell), and U87/CD4 (glioma cell)." (PMID 18577234, 2008). "Faint signals of FPRL1 mRNA were detected in HOS (osteosarcoma), U87/CD4 (CD4-transduced glioma cell line) cells, and PBLs." (PMID 18577234, 2008). "We detected mRNA expression of FPRL1 in 293T (embryonal kidney cell line), C8166 (T cell line), HOS (osteosarcoma cell line), Molt4#8 (T cell line), U251MG (astrocytoma cell line), U87/CD4 (CD4-transduced glioma cell line), and peripheral blood lymphocytes." (PMID 18577234, 2008). "Notably, MARCH8 expression was highly positively correlated with CD4+ T memory resting cells in 33 cancer types, but negatively in glioma (GBMLGG)." (PMID 39881438, 2025). ",12 (R)-2HG in the TME may impair production of IFNγ and IL-2 by CD4+ and CD8+ T cells as well as impacting myeloid cell populations, for example immunosuppressive glioma-associated macrophages generated due to altered tryptophan metabolism." (PMID 41138165, 2025). "We studied the infiltration of CD8+ T cells and CD4+ T cells in the glioma." (PMID 41381536, 2025). "CD4+ FoxP3+ Tregs increase in developing gliomas and have an active phenotype." (PMID 40060757, 2025). "CD4+ T cells are integral components of the immune response within the glioma microenvironment." (PMID 41272822, 2025). "Importantly, depletion of Tregs has previously been directly linked to survival prolongation in mice with experimental gliomas, while CD4+/CD25+/FoxP3+ Treg infiltration positively correlates with clinical glioma tumour grade." (PMID 39048947, 2024). "Moreover, multiple studies have reported a significant presence of CD4+ CD25+FoxP3+ T regulatory cells in the glioma microenvironment." (PMID 39452154, 2024). "Since MDSCs are immunosuppressive cells in the TME of gliomas and high levels of MDSC cells have been associated with higher tumor grades of glioma, the proportion of MDSC cells in spleens and tumor tissues are also analyzed by FCM, alongside CD45+, CD4+ and CD8+ T cells." (PMID 39065567, 2024). "Activated CD4+ Tc were even higher in IDH-WT glioma whereas Bc were higher in RRMS patients." (PMID 39497174, 2024). "The results showed that triptolide can reverse the inhibitory effect on CD4+ T cells in the glioma immunosuppressive microenvironment, which was consistent with the Flies group’s investigation that the inhibition of CD4+ T cells mainly accounts for the tumor immunosuppressive microenvironment." (PMID 37375698, 2023). "Moreover, IHC staining was conducted to evaluate the expression of REST and CD4 in normal and glioma tissues with different REST expression." (PMID 36810892, 2023). "In glioma tissue, the infiltrating CD4+ T cells and CD8+ T cells were significantly increased." (PMID 37122727, 2023). "RT-qPCR, western blot, flow cytometry, immunofluorescence, luciferase reporter assay, chromatin immunoprecipitation and ELISA were performed to measure the effect of lactate on the regulation of CD39, CD73 and CCR8 in cultured glioma stem cells, CD4 + T cells or macrophages." (PMID 37770937, 2023). "A variety of peripheral immune cells exist in the glioma microenvironment, including myeloid-derived suppressor cells (MDSCs), natural killer (NK) cells, macrophages, neutrophils, CD4+ helper T (Th) cells, CD8+ cytotoxic T lymphocytes (CTLs), and regulatory T cells (Treg)." (PMID 37152037, 2023). "Furthermore, we randomly selected 12 glioma clinical specimens and detected some immune cell markers, including CD4, FOXP3, CD68, iNOS and CD206, to verify our bioinformatics analysis results." (PMID 37006287, 2023).
glioma (continued). "In gliomas, the infiltrating CD4+ and CD8+ cells represent a low percentage compared to GAM." (PMID 37274252, 2023). "Th1, Th2 and Th 17 CD4+ T cells were hardly seen in IDH mutant gliomas, compared to IDH-WT tumors." (PMID 38012322, 2023). "Besides, glioma cells lack the co-stimulation molecules B7.1/2, and overexpress the PD-L1 mRNA and protein, a potent inhibitor of CD4+ T cell functions." (PMID 37274252, 2023). "In this study, we explored the possibility that some PLINs may have a specific function in the immunological microenvironments of gliomas by presenting a positive correlation with CD4+T cells, CD8+T cells, and macrophage infiltration." (PMID 37189627, 2023). "Expression of most CD4 T subset-associated genes was also not significantly impacted by IDH1 mutation in low grade gliomas." (PMID 37161052, 2023). "In addition, infiltration of B cells, CD4 T cells, NKTs, Tr1s, nTregs, iTregs, Th1s, Th17s, Tfhs, and Tcms was reduced in gliomas with high TMIGD2 levels." (PMID 37261362, 2023). "sDC1 may regulate antigen processing and presentation in gliomas through CTSL or CD4, and thus participate in glioma immune escape." (PMID 37088950, 2023). "Lactate accumulation within cells upregulated CD39, CD73 and CCR8 expressions in both lactate-treated cells and glioma stem cells-co-cultured CD4 + T cells and macrophages, and intracellular lactate directly elevated the activities of these gene promotors through histone H3K18 lactylation." (PMID 37770937, 2023). "On the other hand, a literature review employed single-cell RNA sequencing profiles from murine glioma models to demonstrate a high proportion of CD4(+), CD8(+) T cells, and natural killer cells in LGG samples, whereas this infiltration was absent in HGG samples." (PMID 37759912, 2023). "Our results first suggested that REST expression was significantly positively correlated with immune cells, including B cells, CD8+ T cells, CD4+ immune cells, macrophages, neutrophils, and dendritic cells in glioma, as well as the particular biomarkers of these immune cells." (PMID 36810892, 2023). "CD4+ T-cell deficiency drives CD8+ Tcell exhaustion leading to unresponsiveness to PD-1 blockade, as demonstrated through CD4 depletion in a Gl261-induced glioma mouse model." (PMID 37304294, 2023). "Besides, immune factors are closely associated with the development of glioma, involving Treg, CD3+T, CD4+T and CD8+T cells." (PMID 35431649, 2022). "In addition, the expression of hepcidin in gliomas was closely related to the infiltration of B cells, CD4+ T cells, CD8+ T cells, macrophages, neutrophils and dendritic cells." (PMID 36237302, 2022). "Moreover, Cox proportional hazard analysis showed that populations of B cells, CD8+ T cells, CD4+ T cells, macrophages, neutrophils, and dendritic cells, along with NCAPG expression, were significantly associated with poor OS in glioma patients." (PMID 35280743, 2022). "Systemic T cell suppression via glioma stem cells (GSCs) derived exosomes occurs with internalization by CD14+ monocyte which causes stunted maturation and formation of monocytic MDSCs, subsequently disrupting CD3+ and CD4+ T cell activation." (PMID 36467419, 2022). "Protein–protein network interaction analysis showed that SDC1 may regulate antigen processing and presentation through CTSL or CD4 in glioma." (PMID 35669186, 2022). "Finally, we isolated GFP+S100a4+ CD4+ T cells from S100a4+/- and S100a4−/− host gliomas and co-cultured them for 4 days with in vitro activated, fluorescently-labeled B6 CD3+ splenocytes." (PMID 35140215, 2022). "Studies have shown that CD4+ T cells, B cells, CD8+ T cells, neutrophils, and M2 macrophages play important roles in the occurrence and malignant progression of glioma and that Tregs are closely associated with significant immune suppression in the tumor, thus supporting the results of our study." (PMID 35756689, 2022).
glioma (continued). "The tumor immune microenvironments were strikingly different and WTS revealed high levels of transcripts from myeloid cells as well as M1 and M2 macrophages in the glioma section, while transcripts from CD4+ lymphocytes and NK cells predominated in the epithelioid section." (PMID 36703629, 2022). "Furthermore, glioma-related B7-homologue 1 (B7-H1) was identified as a strong inhibitor for activating CD4+ and CD8+ T-cell, evaluated by the increase of cytokine production, such as IFN-γ, IL-2, IL-10, and the expression of CD69, the T-cell activation marker." (PMID 35269652, 2022). "Likewise, the correlation between naïve CD4(+) T cells and gliomas is unclear and further investigation is needed." (PMID 35592520, 2022). "There is a correlation between granulocytic MDSCs and effector memory CD4+ T cells in gliomas." (PMID 35860278, 2022). "In addition, the high-risk subgroup had increased levels of Tregs, macrophages M0/M1/M2, and neutrophil infiltration and decreased T cell CD4+ naïve, NK activated, and monocyte infiltration, reflecting the local immunosuppressive microenvironment of gliomas." (PMID 35592707, 2022). "In glioma, tumor-infiltrating CD4+ T cells play an important role in immune regulation." (PMID 35280743, 2022). "Previous studies indicated that glioma-derived MDSCs could induce antigen-specific CD4+ tolerance or T cell exhaustion in a mouse model, contributing substantially to dysfunction among activated T cells that successfully arrive at the tumor side." (PMID 36497232, 2022). "BTN2/3 subfamily expression may upregulate the infiltrating levels of CD4+ T and B cells to promote the development of pan-glioma." (PMID 36033440, 2022). "Importantly, we observed a higher density of CD4+ PD-1+ GITs in gp96-high gliomas than in gp96-low gliomas, but this phenomenon did not exist for CD8+ PD-1+ GITs." (PMID 35794988, 2022). "Of note, some cancer types, which had RORs higher than would be predicted by the TMB – CD4+ naive T-cells model, exhibited higher DC abundance (e.g., lung adenocarcinoma), and some with lower-than-predicted RORs showed lower DC abundance (e.g., glioma)." (PMID 36505471, 2022). "On tumor-derived MDSCs, there was a considerable up-regulation of PD-L1, and T-cell co-culture tests revealed that glioma-infiltrating MDSCs might increase PD-1 expression on CD4+ effector memory T-cells." (PMID 35269652, 2022). "Patients with T cell-deficient gliomas presented a longer survival than the T cell-enriched group; nevertheless, CD8+ T cell-dominant group predicted a better survival as compared with the CD4+ T cell-dominant group." (PMID 35203421, 2022). "Moreover, intratumoral accumulation and activation of CD4+FoxP3+ Treg has been considered the principal immune escape mechanism in gliomas." (PMID 34066132, 2021). "In addition, CD4 counts have also been used to monitor immunosuppression due to temozolomide therapy in glioma patients." (PMID 33726710, 2021). "Importantly, EVA1B overexpression was associated with a higher infiltration level of CD4+ T cells, CD8+ T cells, B cells, macrophages, and neutrophils in glioma." (PMID 33889156, 2021). "Moreover, HDAC1 expression positively correlated with neutrophil (r = 0.60, p = 2.88e-47) and CD4+ T cell infiltration (r = 0.52, p = 3.96e-35) in lower-grade glioma." (PMID 34540896, 2021). "And overexpression of SERPINA3 correlated with low CD4+ T cell infiltration in glioma tissues." (PMID 34449972, 2021). "Additionally, low dose metronomic regimens of temozolomide, an alkylating agent, can reduce Treg to total CD4 + T lymphocyte ratios and impair Treg suppressive activity in glioma-bearing rats." (PMID 34702850, 2021). "Infiltrating immune cells in glioma tumor microenvironment are comprised of microglia/macrophages, CD4+ T cells, regulatory T cells (Tregs), MDSCs, and granulocytes, among which microglia and MDSC are the most frequent, contributing to ineffective immune activation in GBM." (PMID 33664747, 2021).
glioma (continued). "The expression of MAP3K8 was positively correlated with the enrichment of memory CD4+ T cells, effector memory CD4+ T cells, plasmacytoid dendritic cells, neutrophils, myeloid dendritic cells, mast cells, macrophages, M2 macrophage, and M1 macrophage in glioma." (PMID 35004849, 2021). "Based on these findings, whether SERPINA3 affects CD4+ T cells in glioma by affecting STAT3 should be further investigated." (PMID 34449972, 2021). "Additionally, we found a greater proportion of infiltrating CD4+CD25+Foxp3+ Tregs in the tumor tissue than in peripheral blood of glioma patients." (PMID 33576874, 2021). "CD4+ T cell play a vital part in the immune procession of glioma." (PMID 34449972, 2021). "have found high levels of TIGIT expression on CD8+ and CD4+ TILs in glioma patients." (PMID 34305910, 2021). "Additionally, we provide evidence of enhanced T-cell response in the brain of mice surviving long-term after tumor induction, specifically CD4+ and effector memory CD4+ T-cells, suggestive of long-term immunity against glioma." (PMID 33002018, 2020). "Almost identical findings were observed in the CD4+ T cells from grade 2 and 3 gliomas." (PMID 32721947, 2020). "Lastly, to explore the possible clinical relevance of CD8+ T cell infiltration, we analyzed CD8 and CD4 RNA expression in datasets with LGG [Brain Lower Grade Glioma (TCGA, Provisional, overlapping patients excluded) and Brain Lower Grade Glioma (TCGA, PanCancer Atlas) samples]30." (PMID 32358581, 2020). "On the contrary, the fraction of naïve B cells, resting dendritic cells, Eosinophils, Neutrophils, M1 macrophages, activated mast cells, follicular helper T cells (Tfh), γδ T cells and resting CD4+ memory T cells was significantly lower in gliomas tissue than normal brain tissue." (PMID 32509446, 2020). "To determine whether A2aR was also upregulated in murine models of glioma, we profiled CD4+ and CD8+ T cells and CD11b+ myeloid cells from the peripheral blood of C57BL/6J mice with established intracerebral GL261 tumors and from healthy control mice." (PMID 32721947, 2020). "A study using an intracranial human glioma xenograft mouse model suggested that CES activity may induce higher peripheral CD4+ und CD8+ T cell degranulation which is a measure of potential immune response." (PMID 30867471, 2019). "In fact, it has previously been established that IDH1R132H can be presented by HLA-DR, and a spontaneous humoral as well as CD4 T cell response may occur in a subset of glioma patients." (PMID 31240524, 2019). "Glioma TILs show a predominant regulatory T-cell population (CD4 + CD25 + Foxp3+)." (PMID 30208949, 2018). "Consistent with pro-tumorigenic M2 GAMs found in human patient samples, dynamic characterization of immune cell populations and transcriptomic analysis of GAMs in C6 rat gliomas definitively identify accumulation of immunosuppressive CD4+ and Treg populations, and high expression of M2 markers." (PMID 32914058, 2018). "In a syngeneic orthotopic murine model of glioma, CD4+ depletion completely nullified tumor lysate vaccine/Fc-OX40L treatment efficacy, and the survival effects were found to be driven in part by antibody-dependent cell mediated cytotoxicity (ADCC) and natural killer T cell (NKT) populations." (PMID 32914058, 2018). "CD4+ T cells infiltrated into the SB28 glioma tumors in the Veh-control mice." (PMID 30262908, 2018). "Although CD4+ cell numbers alone do not directly correlate with clinical outcome in GBM patients, new evidence suggests that elevated CD4+ and/or CD4+FOXP3+ population ratios may be indicative of glioma disease severity and risk of recurrence." (PMID 32914058, 2018). "In glioma, tumor infiltrating lymphocytes (TILs) consisting of CD4+ and CD8+ cells are present." (PMID 30208949, 2018). "Thus, we cultured the glioma-specific Th9 cells (or naïve CD4+ T cells) and GL261 cells together in the presence of DCs." (PMID 28002799, 2017).
glioma (continued). "In addition, IL-9+ CD4+ T cells were observed in the glioma tissue, which were more in mice treated with Ag/SEB, or SEB, or cAg/SEB than those treated with saline or Ag alone." (PMID 28002799, 2017). "It has been reported that infiltrating MDSCs could induce PD1 expression on CD4+ effector memory T cells in glioma." (PMID 29383101, 2017). "Besides the T cells in peripheral circulation, the frequency and expression level of PD-1 are also significantly higher on glioma-infiltrating CD4+ effector memory T cells, when compared with cells from healthy donors." (PMID 27756892, 2017). "Similarly, CD4+FoxP3− T helper and CD4+FoxP3+ T regulatory cells are found clustered together in the glioma." (PMID 21060663, 2010). "In future investigations, we intend to identify whether IL-17A expression in glioma is solely a CD4+ T cell cytokine or if B cells also produce this cytokine through analysis of IL-17A mRNA levels in CD4 T cell- and B cell-deficient mice with malignant glioma." (PMID 21060663, 2010). "Of note, patients with malignant tumors of central nervous system (i.e. gliomas) are characterized by dramatic reductions in CD4+ T cell number and a disproportionate presence of immunosuppressive regulatory T cells, exactly the same features of our mice bearing NPC-derived tumors." (PMID 20436918, 2010). "A CD4-transduced human glioma cell line, NP-2/CD4, is strictly resistant to HIV/SIV infection." (PMID 18577234, 2008). "The study of the correlation between GADD45G expression and the infiltration levels of various immune cells suggests that it may influence the progression of glioma by affecting myeloid-derived suppressor cells, activated CD4 T cells, and CD56bright natural killer cells." (PMID 41018072, 2025). "Furthermore, they also identified that the percentage of TIM-3 positivity was significantly higher on peripheral CD4+ and CD8+ T cells from glioma patients overall (seven out of thirty were glioblastoma patients) compared to CD4+ and CD8+ T cells from healthy controls." (PMID 40072074, 2025). "Negative regulation of CD4+/CD8+ T-cells may restrain T-cell immunity in glioma." (PMID 39866232, 2025). "Regulation of the CD8+ /CD4+ TIL ratio may have treatment implications for gliomas." (PMID 40097979, 2025). "The research findings indicate that IQGAP3 is associated with various immune cell types, particularly with CD4 Th2 cells and MDSCs present in all subtypes of gliomas, and the results of mIHC further validate the hypotheses generated from the bioinformatics analysis." (PMID 38560572, 2024). "Hence, this study suggests that ZIKV can be used as an adjuvant therapy along with vaccination to improve long-term survival of mice with GBM/glioma, as a consequence of CD4+ T-cell response and production of memory T-cells capable of respond selectively to tumor cells." (PMID 39347716, 2024). "Interestingly, SMOC1 expression correlated negatively with infiltration by B cells, CD4 + T cells, CD8 + T cells, macrophages and dendritic cells in LGGs, suggesting that SMOC1 may be associated with the tumor microenvironment of glioma." (PMID 38429655, 2024). "In summary, our current work demonstrated that HK3 could increase the infiltration of M2 macrophages, neutrophils, and various subtypes of activated memory CD4+ T cells into the tumor microenvironment and could be a predictor of the unfavorable prognosis of glioma." (PMID 37779195, 2023). "In this study, the results of the in vivo experiments demonstrated that the overexpression of Hk3 could promote the malignant progression of glioma in mice along with increased infiltration level of M2 macrophages, neutrophils, and various subtypes of activated memory CD4+ T cells." (PMID 37779195, 2023).